NR2C2 (nuclear receptor subfamily 2 group C member 2)
Description:
Orphan nuclear receptor that can act as a repressor or activator of transcription. An important repressor of nuclear receptor signaling pathways such as retinoic acid receptor, retinoid X, vitamin D3 receptor, thyroid hormone receptor and estrogen receptor pathways. May regulate gene expression during the late phase of spermatogenesis. Together with NR2C1, forms the core of the DRED (direct repeat erythroid-definitive) complex that represses embryonic and fetal globin transcription including that of GATA1. Binds to hormone response elements (HREs) consisting of two 5'-AGGTCA-3' half site direct repeat consensus sequences. Plays a fundamental role in early embryonic development and embryonic stem cells. Required for normal spermatogenesis and cerebellum development. Appears to be important for neurodevelopmentally regulated behavior (By similarity). Activates transcriptional activity of LHCG. Antagonist of PPARA-mediated transactivation.
Synonyms: TAK1; TR4; TR2R1; hTAK1
Tractability: Small molecule: a high-quality ligand is known; it has a binding pocket of medium quality; it belongs to a druggable protein family. PROTAC: UniProt records ubiquitination sites on it; ubiquitination databases record sites on it; its protein half-life has been measured; a small molecule that binds it is known.
Target class: Nuclear hormone receptor subfamily 2; Nuclear hormone receptor subfamily 2 group C member 2; Transcription factor; Nuclear receptor; Nuclear hormone receptor subfamily 2 group C
Gene: Protein-coding gene on chromosome 3 (14,947,544 to 15,053,600, forward strand). Ensembl gene ENSG00000177463.
Subcellular location: Nucleus
Subcellular location (Human Protein Atlas): Nucleoplasm
Pathways (Reactome):
Chromatin organization: Interaction of NuRD complexes with transcription factors
Gene expression (Transcription): Nuclear Receptor transcription pathway
Gene Ontology:
Molecular function: DNA-binding transcription activator activity, RNA polymerase II-specific; DNA-binding transcription factor activity; protein binding; RNA polymerase II cis-regulatory region sequence-specific DNA binding; RNA polymerase II transcription regulatory region sequence-specific DNA binding; sequence-specific DNA binding; sequence-specific double-stranded DNA binding; DNA-binding transcription factor activity, RNA polymerase II-specific; nuclear receptor activity; zinc ion binding
Biological process: negative regulation of transcription by RNA polymerase II; positive regulation of canonical NF-kappaB signal transduction; positive regulation of JNK cascade; positive regulation of transcription by RNA polymerase II; tumor necrosis factor-mediated signaling pathway; cell differentiation; nervous system development; positive regulation of embryonic development; regulation of DNA-templated transcription; intracellular receptor signaling pathway
Cellular component: nucleoplasm; chromatin; nucleus
Genetic constraint (gnomAD): Loss-of-function variants: 4 observed, 57.56 expected, observed/expected ratio (o/e) 0.0695, 90% interval 0.033 to 0.16. The upper end of that interval is the gene's LOEUF score, 0.16, which puts it in group 1 of 6, group 1 being the genes least tolerant of losing a copy. Missense variants: 464 observed, 773.38 expected, observed/expected ratio (o/e) 0.6, 90% interval 0.56 to 0.65. Synonymous variants: 265 observed, 278.22 expected, observed/expected ratio (o/e) 0.95, 90% interval 0.86 to 1.05.
Homologues: Orthologues: macaque NR2C2 (100% identical), pig NR2C2 (99% identical), dog NR2C2 (99% identical), rabbit NR2C2 (98% identical), mouse Nr2c2 (98% identical), rat Nr2c2 (98% identical), chimpanzee NR2C2 (96% identical), guinea pig NR2C2 (96% identical), tropical clawed frog nr2c2 (89% identical), zebrafish nr2c2 (81% identical), Caenorhabditis elegans nhr-41 (25% identical), Drosophila melanogaster Hr78 (23% identical), and 25 more. Paralogues in human: NR2C1 (63% identical), NR2F1 (27% identical), NR2F2 (26% identical), RXRA (26% identical), RXRB (24% identical), NR2F6 (24% identical), RXRG (24% identical), NR2E1 (21% identical), HNF4G (21% identical), NR2E3 (20% identical), HNF4A (20% identical).
Diseases named in the same sentence as NR2C2 in open-access papers:
NR2C2 is named in the same sentence as 80 diseases in open-access papers, as found by Europe PMC text mining. Sharing a sentence is not in itself a finding about the gene and the disease. The quoted sentences say what the papers report.
prostate carcinoma (15 papers, 2015 to 2023). A carcinoma that arises from epithelial cells of the prostate gland. "The NR2C2 also increased prostate cancer invasion by altering TGFβR2/p-Smad3 signalling by decreasing miR-373-3p expression and further, promotes prostate cancer metastasis through upregulation of CCL2/CCR2 signalling." (PMID 33113804, 2020). "Nevertheless, previous studies also found that NR2C2 could act as a tumor suppressor by modulating DNA damage/repair systems in prostate cancer." (PMID 34956884, 2021). "In prostate cancer, NR2C2 could prevent or delay prostate tumorigenesis via regulating the ATM expression at the transcriptional level and could suppress prostate cancer invasion via altering the TIMP-1/MMP2/MMP9 signals." (PMID 34956884, 2021). "Indeed NR2C2 has been reported to be a tumor-related gene in genitourinary cancers, including prostate cancer and renal cell carcinoma, but with no report on bladder cancer yet." (PMID 34956884, 2021).
hepatocellular carcinoma (7 papers, 2010 to 2021). A malignant tumor that arises from hepatocytes. "Silencing NR2C2 increased the resistance of hepatoma cells to cisplatin chemotherapy." (PMID 30518750, 2018).
breast carcinoma (6 papers, 2015 to 2020). "In breast cancer, NR2C2 interacts with estrogen receptor to inhibit MCF-7 cell proliferation." (PMID 31223310, 2019). "NR2C1 and NR2C2 levels are lower in breast-cancer than normal tissue." (PMID 26894976, 2016). "The nuclear receptor subfamily members NR2C1 and NR2C2 were found to be down-regulated in breast cancer but were not proposed as prognostic markers for any cancer." (PMID 30020984, 2018). "The few available data do not provide clues as to the relevance of NR2C1 and NR2C2 in breast-cancer, but it can be suggested that the two receptors are anti-oncogenic." (PMID 26894976, 2016).
Insulin resistance (5 papers, 2013 to 2022). Increased resistance towards insulin, that is, diminished effectiveness of insulin in reducing blood glucose levels. "Jazf1 is a zinc finger protein and an inhibitor of the Nuclear receptor subfamily 2, group C, member 2 (Nr2c2), which is involved in insulin resistance, glucose and lipid metabolism, and regulation of peroxisome proliferator-activated receptor (PPAR)α, β/δ, γ." (PMID 32244869, 2020). "Moreover, the NR2C2-knockout mice showed decreased adipose development, obesity-related inflammation, hepatic steatosis, and insulin resistance." (PMID 34407873, 2021). "Thus, JAZF1 might influence metabolic regulation, adipose development, adipocyte differentiation, obesity, and insulin resistance through indirectly NR2C2-mediated transcriptional regulation." (PMID 34407873, 2021).
bladder cancer (4 papers, 2015 to 2021). "The overall survival curve shows that the prognosis of patients with bladder cancer is positively associated with the NR2C2 expression." (PMID 34956884, 2021). "Based on TCGA and GTEx database, we found that the expression of NR2C2 in bladder cancer tissues was lower than that in adjacent normal tissues." (PMID 34956884, 2021). "This study identifies that miR-616-5p can promote bladder cancer progression via altering the expression of NR2C2." (PMID 34956884, 2021). "In this part, we performed a rescue experiment to check the relationship between miR-616-5p and NR2C2 on the phenotype of bladder cancer." (PMID 34956884, 2021). "In this study, we found that miR-616-5p could promote the invasion and migration of bladder cancer cells via suppressing its potential downstream target NR2C2." (PMID 34956884, 2021). "We found that NR2C2 could be a potential downstream target, and we did the invasion and migration assays to verify its function in bladder cancer." (PMID 34956884, 2021). "In our study, we revealed the role of NR2C2 as a tumor suppressor in bladder cancer." (PMID 34956884, 2021). "miR-616-5p could promote bladder cancer invasion and migration via downregulating the NR2C2 expression." (PMID 34956884, 2021). "We found that miR-616-5p could increase the invasion and migration of bladder cancer, but NR2C2 could decrease the invasion and migration of bladder cancer." (PMID 34956884, 2021). "We provided the first evidence that upregulated miR-616-5p could promote bladder cancer invasion and migration by targeting NR2C2." (PMID 34956884, 2021). "Moreover, we found that the expression of miR-616 and NR2C2 was negatively correlated in bladder cancer according to the LinkedOmics database." (PMID 34956884, 2021). "The clinical data further verified our in vitro results that NR2C2 could act as a tumor suppressor for bladder cancer." (PMID 34956884, 2021). "Even though we first found that miR-616-5p could promote bladder cancer invasion and migration via depressing the NR2C2 expression, there are some limitations in this study." (PMID 34956884, 2021). "Importantly, patients with a high expression of NR2C2 showed better prognoses in bladder cancer." (PMID 34956884, 2021). "Moreover, prognostic data based on TCGA database consistently revealed that NR2C2 could act as a tumor suppressor in bladder cancer." (PMID 34956884, 2021). "Therefore, our results suggest that the miR-616-5p/NR2C2 pathway could be a potential therapeutic target for bladder cancer." (PMID 34956884, 2021). "However, whether NR2C2 could correlate with miRNAs to impact bladder cancer progression remains unknown." (PMID 34956884, 2021).
lung carcinoma (4 papers, 2013 to 2025). "The expression of the NR2C2 gene, a potential target of miR-378b, was significantly upregulated in lung cancer tissues." (PMID 41144480, 2025). "It has been reported that long Noncoding RNA CDKN2B-AS1 contributes to development of lung cancer by modulating miR-378b/NR2C2 axis." (PMID 34520391, 2021). "In lung cancer, CDKN2B-AS1 acts as a cavernous body by adsorbing miR-378b and regulating miR-378b/NR2C2 to promote cancer development." (PMID 34712660, 2021).
Pituitary Adenomas (3 papers, 2016 to 2021). "NR2C2 was overexpressed in pituitary adenoma and promoted ACTH secretion, cell proliferation, and tumor invasion." (PMID 31223310, 2019). "High NR2C2 expression was associated with nonfunctioning pituitary adenoma invasion, recurrence, and progression." (PMID 34150649, 2021).
glioma (2 papers, 2018 to 2020). A benign or malignant brain and spinal cord tumor that arises from glial cells (astrocytes, oligodendrocytes, ependymal cells). "We then measured the expression level of NR2C2 mRNA variant 1 in glioma cells." (PMID 30518750, 2018). "Similar to our results, the low expression of NR2C2‐47aa‐uORF in gliomas inhibited cell malignant biological behaviour, but promoted apoptosis." (PMID 32368853, 2020). "Here, we elucidated the function and possible molecular mechanisms of the effect of some ncRNAs and NR2C2-uORF on the biological behaviors of gliomas." (PMID 30518750, 2018). "We also confirmed that NR2C2 was involved in regulating miR-627-5p-inducted inhibition of malignancies in U87 and U251 glioma cells." (PMID 30518750, 2018). "In this study, we first examined the expression levels of uORF, UCA1, miR-627-5p, and NR2C2 in glioma tissues and cell lines." (PMID 30518750, 2018). "This study demonstrated that the NR2C2-uORF impaired the pivotal roles that UCA1-miR-627-5p-NR2C2 feedback loop had in regulating the malignancies of glioma cells by targeting NR2C2 directly." (PMID 30518750, 2018). "Up-regulated NR2C2 impaired apoptosis ability of glioma cells significantly compared with NC group (P < 0.05), while NR2C2 knockdown showed the opposite result (P < 0.05)." (PMID 30518750, 2018). "Western blot assay was used to determine the expression levels of NR2C2, SPOCK1, and NR2C2-uORF in glioma tissues and cells." (PMID 30518750, 2018). "Overexpressed NR2C2 promoted proliferation, migration, and invasion of glioma cells but inhibited apoptosis." (PMID 30518750, 2018). "Based on these results, the interaction among UCA1, miR-627-5p, and NR2C2 in regulating malignant behaviors of gliomas, as well as the role of NR2C2-uORF in this pathway were also explored." (PMID 30518750, 2018). "Compared with the control group, proliferation, migration, and invasion of glioma cells decreased in agomiR-627-5p+NR2C2(−) group (P < 0.05), but increased in antagomiR-627-5p+NR2C2(+) group (P < 0.01)." (PMID 30518750, 2018). "Significant elevation of NR2C2 was observed in glioma tissues and cell lines compared with NBTs and NHA, respectively (P < 0.05)." (PMID 30518750, 2018). "This NR2C2-uORF expressed low in glioma tissue as well as in glioma cell lines and inhibited NR2C2 expression." (PMID 30518750, 2018). "To explore the effect of uORF on NR2C2, we transfected glioma cells with pre-uORF and pre-NC constructs and examined uORF and NR2C2 expression." (PMID 30518750, 2018). "Immunohistochemistry analysis showed that NR2C2-uORF located in the nucleus and it positively correlated with the progression of glioma pathological grades." (PMID 30518750, 2018). "CCK-8 assay was conducted and revealed the increase of proliferation of glioma cells in NR2C2(+) group (P < 0.01), and the decrease in NR2C2(−) group compared with the NC group (P < 0.01)." (PMID 30518750, 2018). "We explored the possible functional roles of NR2C2 in glioma cells after they were transfected with stable silenced and overexpressed constructs." (PMID 30518750, 2018). "As a post-transcriptional regulatory element, NR2C2-uORF inhibited NR2C2 expression from a bypass through inhibiting NR2C2 mRNA expression thereby significantly inhibited the malignant behaviors of glioma cells." (PMID 30518750, 2018). "MiR-627-5p and NR2C2 co-overexpression signifcantly reversed the inhibition effect induced by transfection of agomiR-627-5p alone, revealing that miR-627-5p impaired malignancies of glioma cells by downregulating NR2C2 expression." (PMID 30518750, 2018). "We found that SPOCK1 was involved in NR2C2-induced regulation in glioma cells, whereas overexpression of NR2C2 increased the expression of SPOCK1." (PMID 30518750, 2018). "Our present study found that NR2C2 expression increased in glioma tissues and glioma cells." (PMID 30518750, 2018).
glioma (continued). "To clarify whether the influence of miR-627-5p had on glioma cells was mediated by NR2C2, we cotransfected U87 and U251 cells with miR-627-5p and NR2C2 constructs." (PMID 30518750, 2018). "Moreover, NR2C2 protein expression level was up-regulated in glioma cells compared with NHAs (P < 0.05), and also in glioma tissues compared with NBTs (P < 0.05)." (PMID 30518750, 2018). "RNA expression of NR2C2 in glioma tissues and cells were evaluated by qRT-PCR assay." (PMID 30518750, 2018). "Furthermore, ChIP assay indicated that NR2C2 bound to SPOCK1 promoter and up-regulated SPOCK1 expression, thereby promoting malignant behaviors of glioma cells." (PMID 30518750, 2018). "But the role of NR2C2 in gliomas has not been clearly reported yet." (PMID 30518750, 2018).
renal cell carcinoma (2 papers, 2021). "In renal cell carcinoma, NR2C2 could promote renal cell carcinoma metastasis via HGF/Met and miR490-3p/vimentin signals." (PMID 34956884, 2021).
Azoospermia (1 paper, 2020). Absence of any measurable level of sperm,whereby spermatozoa cannot be observed even after centrifugation of the semen pellet. "Some target genes of the downregulated miRNAs, such as ACVR2A, CCND1, CCNE2, HMGA2, BMI1, NR2C2 and BCL2, have been associated with gonadal development, and germ cell maintenance through different pathways which could be relevant to the molecular mechanisms affected in KS patients with azoospermia." (PMID 32651451, 2020).
cervical cancer (1 paper, 2018). A primary or metastatic malignant neoplasm involving the cervix. "Consequently, to our knowledge the functional association of receptors including CCR6, EPHB2, NR2C1, and NR2C2 with cervical cancer is being proposed for the first time in this study." (PMID 30020984, 2018).
colon cancer (1 paper, 2019). "In colon cancer cell lines, NR2C2 is required for cell survival and its inhibition induces cell death." (PMID 30809968, 2019).
COVID-19 (1 paper, 2022). A disease caused by infection with severe acute respiratory syndrome coronavirus 2. "Furthermore, our research indicates that transcription factors FOXC1, GATA2, YY1, NR2C2, and E2F4 were overexpressed in common DEGs of psychiatric disorders and COVID-19." (PMID 35185890, 2022).
Cushing syndrome (1 paper, 2020). Cushing's syndrome (CS) encompasses a group of hormonal disorders caused by prolonged and high exposure levels to glucocorticoids that can be of either endogenous (adrenal cortex production) or exogenous (iatrogenic) origin. "The nuclear receptor superfamily 2 group C member 2 (NR2C2), also known as testicular nuclear receptor 4 (TR4), has been associated with tumorigenesis in Cushing’s syndrome." (PMID 33333852, 2020).
endometrial stromal tumor (1 paper, 2009). Neoplasms of the endometrial stroma that sometimes involve the myometrium. "The protein functions as a transcriptional repressor of an orphan nuclear receptor (NR2C2) and chromosomal aberrations in the JAZF1 region associate with endometrial stromal tumors." (PMID 19789630, 2009).
Fanconi anaemia (1 paper, 2020). "Recently it has been shown that FANCD2 can form a complex with NR2F2 or NR2C2, independently from the Fanconi anaemia (FA) core complex or monoubiquitination of FANCD2." (PMID 33244044, 2020).
gastric cancer (1 paper, 2020). A primary or metastatic malignant neoplasm involving the stomach. "It was shown that the ZNF207-HER2 fusion protein is oncogenic in gastric cancer, and NR2C2 was shown to prevent MCF7 cell proliferation in an ER dependent manner." (PMID 32707933, 2020).
genitourinary cancers (1 paper, 2021). "Our findings provide further evidence for the regulation between NR2C2 and genitourinary cancers." (PMID 34956884, 2021).
Hypoglycemia (1 paper, 2020). A decreased concentration of glucose in the blood. "NR2C2 widely displays a phenotype of growth retardation, hypoglycemia, and reduced glycogenesis by decreasing the activity of PEPCK." (PMID 33425511, 2020).
liver fibrosis (1 paper, 2025). "This interaction positively modulates the ubiquitination and protein stability of nuclear receptor subfamily 2 group C member 2 (NR2C2), inducing pyroptosis and inflammation in M1 macrophages and aggravating liver fibrosis." (PMID 41373022, 2025).
lupus (1 paper, 2021). "NR2C2 is an integrant of an axis identified to promote abnormal T cell activity on lupus." (PMID 34603282, 2021).
neuroblastoma (1 paper, 2015). Neuroblastoma (NB) is the most common solid, extracranial childhood tumor. "PTPN14 is a tyrosine phosphatase attributed in oncogenesis and is mutated in multiple cancer types while NR2C2 is known to protect neuroblastoma cells from chemotherapeutic drugs such as doxorubicin and etoposide." (PMID 25944692, 2015).
non-small cell lung carcinoma (1 paper, 2018). A group of at least three distinct histological types of lung cancer, including non-small cell squamous cell carcinoma, adenocarcinoma, and large cell carcinoma. "NR2C2 was upregulated in non-small cell lung cancer and was associated with poor prognosis of patients." (PMID 30518750, 2018).